CYP24A1 (cytochrome P450 family 24 subfamily A member 1)
Diseases named in the same sentence as CYP24A1 in open-access papers (continued):
Sharing a sentence is not in itself a finding about the gene and the disease.
Hypercalcemia (continued). "Some CYP24A1 inactivating mutations have been identified in adults with recurrent kidney stone disease and chronic kidney failure, with only a subset known to have hypercalcaemia in childhood." (PMID 33990852, 2022). "CYP24A1 mutations can cause vitamin D-mediated hypercalcemia and pancreatitis." (PMID 35631254, 2022). "The severe hypercalcemia and nephrocalcinosis in children and adults with a loss of function mutation of this gene, which corroborated the phenotype of the CYP24A1 null mouse, strongly supports the clinical significance of calcitriol induction of CYP24A1 in vitamin D responsive tissues." (PMID 34950686, 2021). "CYP24A1 deficiency was recently shown to lead to severe infantile hypercalcemia." (PMID 34752660, 2021). "In addition, a few case reports described women with CYP24A1 defects who developed hypercalcemia during pregnancy, which was associated with prematurity and intrauterine growth retardation." (PMID 34858904, 2021). "The importance of CYP24A1 in the regulation of vitamin D activity has been demonstrated by several reports showing that CYP24A1 mutation leads to excessive calcitriol activity, resulting in hypercalcemia, hypercalciuria, nephrocalcinosis, and nephrolithiasis." (PMID 34835929, 2021). "CYP24A1 is the principal catabolic enzyme in vitamin D pathway; knockout mice to this enzyme are not able to reduce vitamin D levels and its loss causes idiopathic infancy hypercalcemia." (PMID 32834827, 2020). "The mutant CYP24A1 enzymes revealed complete or near-complete loss of function, characterized by a weak binding of 1,25-dihydroxyvitamin D3 to 24-hydroxylase, leading, in the end, to hypercalcemia, nephrolithiasis and pseudovitamin D-deficient rickets." (PMID 33142950, 2020). "It is possible that the hypercalcemia in some patients with granulomatous diseases or lymphomas may have an underlying defect in CYP24A1 activity and its failure to compensate for the increased 1,25(OH)2D production in these diseases." (PMID 32051922, 2020). "We have also reported a patient, presenting with idiopathic infantile hypercalcaemia (IIH), who was diagnosed with biallelic CYP24A1 mutations resulting in the inability to produce 24,25(OH)2D from 25(OH)D, and had an elevated serum 1,25(OH)2D and a persistent state of hypercalcaemia." (PMID 31061425, 2019). "Mutations in the CYP24A1 gene are associated with a partial or total loss of 24-hydroxylase activity, which may result in hypercalcemia." (PMID 30917564, 2019). "Also in humans loss-of-function mutations in the CYP24A1 are a main cause of the impaired vitamin D catabolism and lead to idiopathic infantile hypercalcemia or hypercalciuric nephrocalcinosis and nephrolithiasis." (PMID 29771914, 2018). "In conclusion, the 25(OH)D/24,25(OH)2D ratio is an unambiguous marker for vitamin D catabolism and may identify patients with hypercalcaemia secondary to CYP24A1 mutations, such as patients with IIH." (PMID 29652819, 2018). "Recent evidence has identified loss of function mutations in CYP24A1, encoding the vitamin D-24-hydroxylase which regulates the catabolism of 1,25(OH)2D, can result in high circulating levels of 1,25(OH)2D, hypercalcemia, hypercalciuria, and nephrolithiasis in humans." (PMID 28335477, 2017). "Thus, as seen in this case, even routine low doses may act as triggers for stone disease and hypercalcaemia in patients with CYP24A1 variants." (PMID 40917505, 2025). "This highlights the importance of considering CYP24A1 variants not only in younger individuals with classic symptoms, but also in older patients who may exhibit mild or atypical signs, such as unexplained hypercalcemia, nephrocalcinosis, or kidney stones." (PMID 40917505, 2025). "We speculate that the inducible UbcCreERT2Cyp24fl/fl that we engineered avoided hypercalcemia because their healthy and normal kidney development enabled them to efficiently excrete their excess calcium load in the urine when Cyp24a1 deficiency was induced in adulthood." (PMID 39688907, 2024).
Hypercalcemia (continued). "Similarly, polymorphisms affecting CYP24A1 have been implicated in the idiopathic hypercalciuria phenotype, which is predisposed to nephrolithiasis and nephrocalcinosis, with increased susceptibility to vitamin D-mediated hypercalcemia." (PMID 39337491, 2024). "Since then, multiple pathogenic variants (PVs) in the CYP24A1 gene have been identified, revealing that the spectrum of biallelic variants (either homozygous or compound heterozygous) ranges from severe hypercalcaemia in infants to mild hypercalcaemia in adults." (PMID 38665259, 2024). "In general, pathogenic CYP24A1 mutations are relatively rare but in view of the high prevalence of vitamin D supplementation during preconception and pregnancy, affected women are at particularly high risk of severe hypercalcemia and associated obstetrics complications." (PMID 35745247, 2022). "In the case of pathogenic CYP24A1 mutations, it appears logical to assume that the degree of hypercalcemia may be, as in the case of PHPT, associated with the risk of obstetric complications although we cannot definitely claim this due to relatively few reported cases." (PMID 35745247, 2022). "Mice that lack global Cyp24a1 expression (Cyp24a1-KO) have hypervitaminosis D, hypercalcemia, and secondary hyperparathyroidism that can lead to death, however a renal-specific deletion has not been created." (PMID 39229197, 2024). "The development of fetal hypercalcemia confirms that the phenotype of Cyp24a1 ablation begins in utero." (PMID 38577520, 2024). "Subsequently, biallelic pathogenic variants in CYP24A1 were also discovered in adults with elevated vitamin D, suppressed parathyroid hormone (PTH), hypercalcemia, hypercalciuria, osteopenia, and recurrent calcium nephrolithiasis." (PMID 38765596, 2024). "Most experimental mice with global Cyp24a1 deletion fail to survive the perinatal period, presumably due to severe hypercalcemia in utero or postnatally." (PMID 39688907, 2024). "CYP24A1-knockout mice manifested severe hypercalcemia, as well as ossification of bone due to the apparently low ability to catabolize 1,25(OH)2D." (PMID 38887504, 2024). "Hypophosphatemia together with decreased concentration of FGF23 leads to the stimulation of 1α-hydroxylase (CYP27B1) and inhibition of CYP24A1, that results in an increment of 1,25(OH)2D3 levels, leading to hypercalcemia and hypercalciuria." (PMID 38504242, 2024). "Mice that lack global Cyp24a1 expression (Cyp24a1-KO) have hypervitaminosis D, hypercalcemia, and secondary hyperparathyroidism that can lead to death; however, a renal-specific deletion has not been successfully created." (PMID 39363152, 2024). "Kidney-specific deletion of Cyp24a1 in Six2CreCyp24fl/fl mice resulted in mild hypercalcemia, but serum phosphate levels were unchanged." (PMID 39688907, 2024). "In this study, we found that ablation of Cyp24a1 increased fetal calcitriol, which was accompanied by hypercalcemia, modest hypophosphatemia, increased FGF23, and normal skeletal development and mineralization." (PMID 38577520, 2024). "Other topics seem to have a good trend after 2010, including those relating to hypercalcemia, CYP24A1, and mendelian randomization." (PMID 36672957, 2023). "This was used in patients with mutations of CYP24A1 and SLC34A3 gene, leading to persistently raised 1,25-dihydroxyvitamin D, hypercalcemia, hypercalciuria, and nephrocalcinosis/nephrolithiasis." (PMID 37274338, 2023). "It has recently been shown that extra-renal CYP24A1 ameliorates severe hypercalcemia in mice with kidney-specific CYP24A1 ablation." (PMID 38201240, 2023). "Mutations in CYP24A1 can result in elevated 1,25(OH)2D causing parathyroid hormone (PTH)-independent hypercalcemia, hypercalciuria, nephrolithiasis, and nephrocalcinosis." (PMID 37701149, 2023).
Hypercalcemia (continued). "Awareness must be increased among clinicians that in the event of hypercalcemia with low PTH concentrations and in patients with nephrolithiasis and/or nephrocalcinosis, pathogenic CYP24A1 mutations should be considered as a potential underlying disease." (PMID 35745247, 2022). "Importantly, pregnancy may be a trigger factor for the development of hypercalcemia in affected patients with pathogenic CYP24A1 mutations, but data on this topic are extremely rare and there exists a knowledge gap regarding guidance for the management of affected patients in this setting." (PMID 35745247, 2022). "The importance of this inactivation step, mediated by CYP24A1, was highlighted in CYP24A1 knockout mice showing impaired intramembranous bone mineralization and hypercalcemia, leading to a lethal phenotype in 50% of the mice." (PMID 35406562, 2022). "Often, corticosteroids are used for the treatment of symptomatic hypercalcaemia as they can inhibit enteral calcium absorption and induce CYP24A1 expression." (PMID 33990852, 2022). "We observed a majority of biallelic mutations in CYP24A1, in accordance with our inclusion criteria (low serum PTH and medical history of hypercalcemia and/or hypercalciuria)." (PMID 34721296, 2021). "Cyp24a1 knockout mice highlighted the important role of this hydroxylase in the catabolism of vitamin D, as these mice showed severe hypercalcemia with about 50% perinatal mortality." (PMID 29771914, 2018). "The importance of CYP24A1-driven calcitriol inactivation was underscored by the finding of impaired intramembranous bone mineralization and hypercalcemia in Cyp24a1 knockout mice, leading to perinatal death in 50% of the mice." (PMID 29657326, 2018). "Genetic testing for CYP24A1 mutation, which can impair vitamin D metabolism and contribute to postpartum hypercalcemia, was initiated; however, the results were negative." (PMID 41487858, 2025). "However, biallelic mutations in the CYP24A1 and SLC34A1 genes have a completely different mechanism leading to hypercalcemia." (PMID 40943461, 2025). "Whereas CYP24A1 induction with glucocorticoids does not sufficiently work in patients with genetically reduced CYP24A1 activity, fluconazole and ketoconazole have both been shown to reduce 1,25(OH)2D3 and normalize hypercalcemia in CYP24A1-deficient patients." (PMID 41009532, 2025). "In experimental mice, the absence of CYP24A1 causes 50% postnatal mortality due to severe hypercalcemia, accompanied by markedly elevated calcitriol and undetectable PTH." (PMID 40565034, 2025). "The most common KSD-associated VUS were sucrase-isomaltase deficiency (SI, N = 8), Wilson disease (ATP7B, N = 7), pseudoxanthoma elasticum and generalized arterial calcification of infancy (ABCC6, N = 5), CYP24A1-related hypercalcemia (CYP24A1, N = 4), and hypouricemia Renal 1 (SLC22A12, N = 4)." (PMID 40126616, 2025). "A study in a child with idiopathic infantile hypercalcemia due to pathogenic variants of CYP24A1 revealed a reduction in 1,25(OH)2D with short-term treatment with rifampin; however, hypercalcemia did not improve." (PMID 40765620, 2025). "However, in the case of a 44-year-old patient with intermittent hypercalcaemia and two intron−exon splice junction mutations (IVS5 + 1G>A and IVS6–2A>G) of CYP24A1, an analysis of family members suggested autosomal dominant inheritance with partial penetrance." (PMID 38665259, 2024). "In conclusion, loss of Cyp24a1 in fetal mice causes hypercalcemia, modest hypophosphatemia, and increased FGF23, but no alteration in skeletal development." (PMID 38577520, 2024). "Absence of Cyp24a1 in mice causes postnatal lethality in about 50% of neonates due to severe hypercalcemia (twice the wildtype [WT] value), which is accompanied by a marked elevation in calcitriol and undetectable PTH." (PMID 38577520, 2024). "Hypercalcaemia related to the presence of PVs in the CYP24A1 gene is often overlooked." (PMID 38665259, 2024).
Hypercalcemia (continued). "In the context of vitamin D-mediated hypercalcemia, glucocorticoids may be used to decrease intestinal calcium absorption to correct serum calcium levels, while the induction of CYP24A1 may help to decrease active vitamin D metabolites’ half-lives." (PMID 39337491, 2024). "A case involving a heterozygous pathogenic variant of CYP24A1 and primary hyperparathyroidism leading to severe hypercalcemia has not been previously reported." (PMID 37909006, 2023). "CYP24A1 deficiency contributes to unexplained vitamin D-mediated hypercalcemia or patients without baseline hypercalcemia or nephrocalcinosis." (PMID 35631254, 2022). "They identified loss-of-function mutations in cytochrome-P450 family 24 subfamily A member 1 (CYP24A1) with an indication for autosomal recessive inheritance in affected children who were particularly prone to develop hypercalcemia after high dose vitamin D supplementation." (PMID 35745247, 2022). "The currently available Cyp24a1 knockout strain developed more than 20 years ago exhibits hypercalcemia, hypercalciuria, and nephrocalcinosis and could represent a model of HCINF1." (PMID 35956396, 2022). "Subsequently, the low levels of serum phosphate and FGF23 induce increases in CYP27B1 expression and 1a-hydroxylase activity; while inhibiting CYP24A1 expression and 24-hydroxylase activity, which have the combined effect of increasing 1,25-(OH)2D3 and hypercalcaemia." (PMID 33990852, 2022). "However, the present pig trial showed a marked increase in CYP24A1 expression in the kidney, suggesting calcitriol elimination in H animals which contributes to the prevention of hypercalcemia and hyperphosphatemia." (PMID 36005601, 2022). "The vast majority of newborns of mothers with hypercalcemia due to CYP24A1 mutations in pregnancy is not affected by idiopathic infantile hypercalcemia, as this disease typically follows an autosomal recessive inheritance pattern." (PMID 35745247, 2022). "Of note, CYP24A1 biallelic mutations were also found in 4 adult patients with medical history of hypercalcemia without nephrocalcinosis nor renal stones." (PMID 34721296, 2021). "The main known role of CYP24A1 (the 1,25-dihydroxy vitamin D 24-hydroxylase) enzyme, a mixed-function oxidase cytochrome P450 molecule, is to catabolize both the active form of vitamin D 1,25D and its precursor 25D, in order to prevent hypercalcemia." (PMID 35008598, 2021). "In humans, inactivating mutations in CYP24A1 is now recognized as a major cause of idiopathic infantile hypercalcemia (IIH), a syndrome marked by severe hypercalcemia, hypercalciuria, and nephrocalcinosis, decreased PTH, low 24,25(OH)2D, and inappropriately normal to high 1,25(OH)2D." (PMID 32051922, 2020). "Infants suffering from this disorder display severe hypercalcaemia and suppressed PTH levels due to their severely impaired capacity to catabolise 25(OH)D and 1,25(OH)2D, as a result of an inactivating mutation in the gene coding for CYP24A1." (PMID 29652819, 2018). "Systemic inhibition of CYP24A1 can result in hypercalcemia and thus we sought to identify a CYP24A1 resistant VDR agonist, which could be given in sufficient quantities to reduce VCaP xenograft growth." (PMID 28591703, 2017). "In conclusion, we suggest that molecular testing for CYP24A1 and SLC34A1 mutations should be performed in each case of idiopathic hypercalcemia/hypercalciuria, both in children and adults, to determine the proper way for acute treatment and complications prevention." (PMID 28470390, 2017). "Owing to the observational nature of available evidence, limited clinical data, and heterogeneous recommendations, there is no standardized approach to managing hypercalcemia in pregnancy secondary to pathogenic CYP24A1 mutations, and pharmacologic options must take fetal exposure into account." (PMID 41377203, 2025).
Hypercalcemia (continued). "Although most hereditary vitamin D metabolism disorders are manifested in childhood, loss-of-function mutations in the CYP24A1 gene, leading to inability to inactivate 1,25(OH)2D, may cause mild hypercalcaemia and not be diagnosed until adulthood." (PMID 40502410, 2025). "Interestingly, there is a report of a patient with CYP24A1-associated hypercalcemia and normal (non-suppressed PTH), who had an enlarged parathyroid gland removed with persistent hypercalcemia and then suppression of PTH." (PMID 40765620, 2025). "In patients with PTH-independent hypercalcaemia, the measurement of vitamin D metabolites using LC–MS/MS analytical technique, followed by genetic testing (e.g., NGS technique), may help to identify carriers of CYP24A1 mutations." (PMID 38665259, 2024). "However, there is no guarantee that these will continue and they might be replaced with other topics, such as hypercalcemia and CYP24A1, since these appeared to be co-cited clusters and also appeared in trending topics." (PMID 36672957, 2023). "Azole agents (e.g., fluconazole or ketoconazole) and rifampin have not been used to treat hypercalcemia during pregnancy and postpartum in patients with pathogenic CYP24A1 mutations, but have been suggested as potential candidates for long-term treatment in this setting." (PMID 35745247, 2022). "Although the reported data are not sufficient for a final evaluation of the genetic mode of CYP24A1 and SLC34A1-related hypercalcemia, clinical evaluation and long-term observation are important for patients carrying monoallelic variants." (PMID 38504242, 2024). "Importantly, glucocorticoids may not be effective in treating hypercalcemia in patients with CYP24A1 mutations for non-pregnant patients." (PMID 35745247, 2022). "However, some factors may limit the usefulness of active vitamin D or vitamin D analogue therapy, such as the resultant hypercalcemia and the inappropriately high levels of CYP24A1 activity, which, besides the deactivation of 1,25(OH)2D3, also have the potential to deactivate vitamin D analogues." (PMID 35883516, 2022). "In the kidney, the induction of CYP24A1 was considered for decades the most critical action of the calcitriol/VDR complex, as it maintains serum calcitriol within normal limits to prevent hypercalcemia and hyperphosphatemia." (PMID 34950686, 2021). "Two challenges that limit VDR agonist use clinically are hypercalcemia and the cooperation of VDR with ERG to hyper-induce the 1α,25-dihydroxyvitamin D3 metabolizing enzyme, CYP24A1, thus reducing VDR activity." (PMID 28591703, 2017). "Corticosteroids are favored postpartum because they effectively treat vitamin D-driven hypercalcemia, do not accumulate in bone, have minimal transfer into breast milk, and are safer for short-term use, including when CYP24A1 abnormalities are present." (PMID 41487858, 2025). "When CYP24A1 activity is marginal or lacking in humans a detrimental hypercalcemia occurs with coincidently low 24,25 (OH)2D3 and high 25 (OH)D3 concentrations in plasma." (PMID 38756523, 2024). "Previously, 1,25(OH)2D3 analogue-derived specific CYP24A1 inhibition was shown to significantly lower PTH levels in normal rats without hypercalcemia." (PMID 35883516, 2022). "Only two cases with hetero-isodisomy also present hypercalcemia associated with low PTH, suggestive of IH phenotype; without confirmation of the involvement of the CYP24A1 gene." (PMID 33952337, 2021). "VDRM2 significantly reduces TMPRSS2:ERG positive VCaP xenograft tumor growth without causing hypercalcemia or significant weight loss in mice and VDRM2 is stable in cells that overexpress CYP24A1." (PMID 28591703, 2017). "In this study, we have tested a novel nonsecosteroidal VDR agonist, VDRM2, which has a large safety margin against hypercalcemia and is not predicted to be a substrate for CYP24A1." (PMID 28591703, 2017).